NPRL3 (NPR3 like, GATOR1 complex subunit)
Diseases named in the same sentence as NPRL3 in open-access papers (continued):
Sharing a sentence is not in itself a finding about the gene and the disease.
focal epilepsy (22 papers, 2018 to 2025). "Haploinsufficiency of the genes (DEPDC5, NPRL2, NPRL3) that make up the GATOR1 complex has recently emerged as a prevalent cause of mostly focal epilepsies." (PMID 39062615, 2024). "Mutations in GATOR1-RagA/B-mTORC1 pathway-related genes (DEPDC5, NPRL2, and NPRL3) have been reported in over 180 families with focal epilepsy, with DEPDC5 mutations being the most common, accounting for 85% of all cases." (PMID 38966089, 2024). "In a 7-year-old girl (E55) with focal epilepsy and a normal brain MRI, we identified a novel de novo variant (c.629 + 1G > T, Clinvar ID 1489034) in the NPRL3 gene." (PMID 38328757, 2023). "We report two rare mutations in the NPRL3 gene in two unrelated Chinese families with focal epilepsy in this study." (PMID 36685832, 2022). "A likely pathogenic variant (c.1300delG, p.(Val434Serfs*23)) in the NPRL3 gene was identified in one patient in our cohort with focal epilepsy." (PMID 35888005, 2022). "It has been reported that focal epilepsy is associated with mutations in the NPRL3 gene in some cases." (PMID 36685832, 2022). "Pathogenic loss of function variants in the NPRL3 gene have been reported in patients and families with focal epilepsy." (PMID 35888005, 2022). "NPRL3 is a known regulator of mTOR activity that promotes neuronal survival in stroke patients and is associated with focal epilepsy." (PMID 33202874, 2020). "With over 180 unrelated families described to date, genes of the GATOR1-mTORC1 pathway (DEPDC5, NPRL2, and NPRL3) are collectively the most frequently mutated genes in focal epilepsies, among which DEPDC5 is predominantly found (85% of all cases)." (PMID 30093711, 2019). "Two other studies identified several NPRL2 and NPRL3 mutations in both sporadic and familial focal epilepsies using targeted gene panel sequencing." (PMID 28082152, 2018). "Recently, an increasing number of presumably pathogenic mutations of the NPRL3 gene were reported in the cases of focal epilepsy, such as frontal lobe epilepsy (FLE), benign epilepsy in children with centrotemporal spikes (BECT), and familial focal epilepsy with variable foci (FFEVF)." (PMID 36937533, 2023). "Five heterozygous mutations in the NPRL3 gene (c.275G>A/p.R92Q; c.745G>A/p.E249K; c.835_836insT/p.S279Ffs*52; c.954_955insCCCA/p.W319Pfs*1; and c.1376_1377insAC/p.S460Pfs*20) was identified in 404 unrelated patients with focal epilepsy using WES analysis." (PMID 36685832, 2022). "An NPRL3 pathogenic mutation was discovered by whole exome sequencing in a family including four subjects with focal epilepsy, two of whom had focal cortical dysplasia type IIa, and later identified in two additional unrelated patients with focal cortical dysplasia type IIa." (PMID 28082152, 2018). "Recent studies have linked mutations in several genes involved in the mTOR signaling pathway - such as TSC1, TSC2, MTOR, DEPDC5, NPRL2, and NPRL3 - to the development of focal epilepsies in affected individuals." (PMID 40546503, 2025). "Among the etiologies of focal epilepsy, mutations of the GATOR1 complex genes—comprising NPRL3, NPRL2, and DEPDC5—are known to result in overactivation of mTORC1." (PMID 40971258, 2025). "In recent years, the GATOR1 complex has been shown to play an important role in the pathogenesis of focal epilepsies, with DEPDC5 exhibiting a higher mutation frequency (approximately 85% of reported cases) than NPRL2 (5%) and NPRL3 (10%)." (PMID 41469379, 2025). "These included DEPDC5, which together with NPRL3 reinforces a haploinsufficiency mechanism for GATOR1-related focal epilepsies." (PMID 36865150, 2024). "Familial focal epilepsy with variable foci (FFEVF) is a rare type of focal epilepsy syndrome; it is associated with NPRL3 variant." (PMID 37099548, 2023).
focal epilepsy (continued). "NPRL3 (nitrogen permease regulator 3‐like protein, OMIM * 600928) haploinsufficiency has recently emerged as a relevant cause of focal epilepsies." (PMID 37491868, 2023). "Overall, germline variants in the GATOR1 complex genes (DEPDC5, NPRL3, and NPRL2) are present in ~10% of focal epilepsy cases, which can be familial or sporadic, especially in familial focal epilepsy with variable foci (FFEVF)." (PMID 34376795, 2022). "The other interesting gene identified was NPRL3 (case 10), which involves the mTOR pathway and an increasingly important gene identified in the drug-resistant focal epilepsies." (PMID 35888005, 2022). "In 2016, mutations related with focal epilepsies, familial cortical dysplasia and SUDEP were also reported for Nprl2 and Nprl3." (PMID 34685669, 2021). "Further analysis revealed that FEFS + /FS had a lower frequency of null mutation than MCD or other focal epilepsies; and missense mutations associated with FEFS + /FS were located away from the binding sites to NPRL2/NPRL3 or RAGA/RAGC." (PMID 32848577, 2020). "We have documented 10 patients with focal epilepsy carrying pathogenetic variants (8/10) or variants of uncertain significance (2/10) in the mTORC1 pathway genes (DEPDC5, NPRL3, and MTOR) who developed central apnea in 100% of their seizures, for a total of 31 seizures with respiratory alterations." (PMID 40971258, 2025). "Haploinsufficiency of NPRL3, either by deletion or a pathogenic variant, is associated with a variable phenotype of focal epilepsy, with or without malformations of cortical development, with known decreased penetrance." (PMID 39062615, 2024). "Mutations in the GATOR1 complex genes, DEPDC5 and NPRL3, play a major role in the development of lesional and non-lesional focal epilepsy through increased mTORC1 signalling." (PMID 36639812, 2023). "Familial focal epilepsy with variable foci (FFEVF) is considered one of the most common forms of autosomal dominant epilepsy caused by mutations in the DEP domain containing 5 (DEPDC5), NPR2 like (NPRL2), and NPR3 like (NPRL3)." (PMID 36685832, 2022). "Pathogenic or likely pathogenic variants in the DEPDC5, NPRL2 and NPRL3 genes were identified in 8–11% of individuals within focal epilepsy cohorts, mostly comprised of familial non-lesional cases." (PMID 34632383, 2021). "The role of NPRL3 in this disease is most probably related with its function in focal epilepsies that might occur in ischemic cerebrovascular disorders." (PMID 34685669, 2021). "Consistent with previous work and current knowledge of focal epilepsy, TMS and MRS here revealed no changes in physiological and biochemical factors of GABAergic transmission in DEPDC5 and NPRL3-related epileptic mTORopathies." (PMID 36639812, 2023).
familial focal epilepsy (4 papers, 2018 to 2025). "Furthermore, the present study confirmed the role of NPRL3 as a cause of familial focal epilepsy." (PMID 36685832, 2022). "Only recently, new genes for familial focal epilepsy (FFE) have been reported from the GATOR1 pathway (DEPDC5, NPRL2, NPRL3) and these were missing from earlier versions of the gene panel CHE-46, CHE-76, CHE-85)." (PMID 29760947, 2018).
α-thalassemia (3 papers, 2023 to 2025). "As α-globin enhancers are required for α-globin expression on the allele in cis, Nprl3+/AEKO is equivalent to the expression of 2 of 4 functional α-globin genes (such as in α0-thalassaemia carriers and alpha-thalassaemia mice, including Hbath-J (− −/aa))." (PMID 40128524, 2025). "NPRL3 is located on chromosome 16p13.3, which is adjacent to the α-globin gene cluster, responsible for α-thalassemia when mutated or deleted." (PMID 39062615, 2024). "Conversely, any individual with full gene deletion of NPRL3 would consequently be (at least) a carrier of α-thalassemia, due to the co-occurring deletion of MSC-R2." (PMID 39062615, 2024). "Our findings also highlight the impact of disruptions in regulatory regions in genetic disorders: any individual with full gene deletion of NPRL3 would have, at a minimum, α-thalassemia trait, due to the presence of the major regulatory element of α-globin genes overlapping the gene’s introns." (PMID 39062615, 2024).
Alpha-thalassemia (2 papers, 2024). Alpha-thalassemia is an inherited hemoglobinopathy characterized by impaired synthesis of alpha-globin chains leading to a variable clinical picture depending on the number of affected alleles. "Two case-control studies evaluated the effect of alpha-thalassemia (α−3.7 or α−4.2 allele), HbS haplotypes, or genetic variants in BCL11A or NPRL3 on the occurrence of hyposthenuria." (PMID 38791464, 2024).
Focal cortical dysplasia (2 papers, 2023 to 2024). A type of malformation of cortical development that primarily affects areas of neocortex. "A third child with germline NPRL3 variant inherited from their unaffected mother resulted in a sibling being diagnosed with the variant who later developed seizures secondary to focal cortical dysplasia." (PMID 39442533, 2024).
frontal lobe epilepsy (2 papers, 2022 to 2023). A localization-related (focal) form of epilepsy characterized by seizures which arise in the frontal lobe. "The majority of patients harboring NPRL3 variants present with frontal lobe epilepsy, either alone or in the context of a SHE or FFEVF syndrome." (PMID 37491868, 2023).
ischemic stroke (2 papers, 2020 to 2021). A stroke disorder caused by obstruction of blood flow to the brain, due to thrombotic (local blood clot formation) or embolic (due to a blood clot or other material traveling from another site) event. "In our ischemic stroke subgroup analysis, we found several associations between the NPRL3 and MPG polymorphisms and stroke subtype." (PMID 33202874, 2020). "For example, our results showed that the NPRL3 rs2541618 C>T polymorphism was associated with the prevalence of ischemic stroke: the NPRL3 rs2541618 TT genotype and the dominant model (CC vs. CT+TT) were both associated with ischemic stroke prevalence." (PMID 33202874, 2020). "Although we did not identify the cause of the high mortality of stroke patients with the NPRL3 rs2541618 CT+TT dominant model, our analysis did show that the NPRL3 rs2541618 polymorphism was significantly associated with the rate of ischemic stroke patient survival." (PMID 33202874, 2020). "Consequently, the NPRL3 gene has been previously linked to ischemic stroke prevalence due to its relationship with cerebrovascular disease." (PMID 33202874, 2020). "Similarly, the NPRL3 rs75187722 G>A polymorphism was associated with ischemic stroke prevalence, and the NPRL3 rs75187722 GA genotype and the dominant model (GG vs. GA+AA) were also significantly associated with ischemic stroke prevalence." (PMID 33202874, 2020). "Furthermore, we confirmed that the NPRL3 rs2541618 and rs75187722 polymorphisms were significantly associated with fibrinogen and uric acid, which are risk factors of ischemic stroke." (PMID 33202874, 2020). "Using an analysis of variance (ANOVA), we confirmed that the NPRL3 rs75187722 AA genotype was associated with increased uric acid levels compared to the uric acid levels with the NPRL3 rs75187722 GG genotype (GG vs. GA vs. AA; P = 0.028) in ischemic stroke patients." (PMID 33202874, 2020). "Therefore, we hypothesized that NPRL3 polymorphisms affect ischemic stroke prevalence and prognosis." (PMID 33202874, 2020). "In agreement with our hypothesis, our analyses showed that the NPRL3 rs2541618 C>T and NPRL3 rs75187722 G>A genotypes were significantly associated with the prevalence of ischemic stroke, and this association was strengthened when limited to ischemic stroke patients with SVD." (PMID 33202874, 2020). "We investigated the NPRL3 rs2541618 C>T, NPRL3 rs75187722 G>A, MPG rs2562162 C>T, and MPG rs710079 C>T polymorphisms in patients with ischemic stroke and controls, as well as by stoke subtype (LAD, SVD, and CE)." (PMID 33202874, 2020). "Our final analysis investigated the relationships between the NPRL3 and MPG polymorphisms and survival in ischemic stroke patients." (PMID 33202874, 2020). "Taken together, these results suggest that NPRL3 and MPG polymorphisms play a role in ischemic stroke." (PMID 33202874, 2020). "To this end, we selected four polymorphisms (NPRL3 rs2541618 C>T, NPRL3 rs75187722 G>A, MPG rs2562162 C>T, and MPG rs710079 C>T) to investigate with respect to ischemic stroke in a Korean population." (PMID 33202874, 2020). "In conclusion, we found that the NPRL3 rs2541618 C>T, NPRL3 rs75187722 G>A, and MPG rs2562162 C>T genotypes were all strongly associated with ischemic stroke prevalence." (PMID 33202874, 2020). "Our study showed that NPRL3 and MPG polymorphisms are associated with ischemic stroke prevalence and ischemic stroke survival." (PMID 33202874, 2020). "We found that two NPRL3 polymorphisms (rs2541618 C>T and rs75187722 G>A), as well as the MPG rs2562162 C>T polymorphism, were significantly associated with ischemic stroke." (PMID 33202874, 2020). "Chang Soo Ryu found that NPRL3 is a common biomarker for ischemic stroke." (PMID 34970268, 2021). "Thus, we designed a case-control study to investigate the association between the NPRL3 and MPG polymorphisms and ischemic stroke in a Korean population." (PMID 33202874, 2020).
ischemic stroke (continued). "Consequently, we identified associations between the NPRL3 rs2541618 C>T, NPRL3 rs75187722 G>A, and MPG rs2562162 C>T polymorphisms with the prevalence of ischemic stroke in a Korean population as well as a significant association between NPRL3 and MPG gene polymorphisms and post-stroke mortality." (PMID 33202874, 2020). "In addition, although it was not significant, the T-A allele combination of the NPRL3 rs2541618 C>T/rs75187722 G>A polymorphisms showed a trend toward increasing ischemic stroke prevalence." (PMID 33202874, 2020). "Finally, we found that the dominant models of NPRL3 rs2541618, NPRL3 rs75187722, and MPG rs2562162 all showed synergistic effects with clinical risk factors of the SVD subtype and ischemic stroke, including platelet level, fibrinogen, hypertension, and diabetes mellitus." (PMID 33202874, 2020). "Especially, NPRL3 rs2541618 CT+TT with hypertension (AOR, 3.120; 95% CI, 2.116–4.599) was shown to significantly increase ischemic stroke prevalence." (PMID 33202874, 2020). "Additional studies such as the replication study are needed to confirm that the NPRL3 and MPG genes play a crucial role in ischemic stroke pathogenesis and to provide more evidence that the regulation of NPRL3 and MPG expression or activation can be used as a tool to prevent ischemic stroke." (PMID 33202874, 2020). "In addition, NPRL3 rs2541618 CT+TT with diabetes mellitus (AOR, 2.904; 95% CI, 1.758–4.796) was shown to significantly increase ischemic stroke prevalence." (PMID 33202874, 2020). "Taken together, these findings suggest that NPRL3 and MPG genotypes may be useful clinical biomarkers for ischemic stroke development and prognosis." (PMID 33202874, 2020).
microcytic anemia (2 papers, 2023 to 2024). Anemia in which the red blood cell volume is decreased. "In multivariate analysis, NPRL3 rs191086839 was observed to have the strongest effect on various erythrocyte indices, including MCV and MCH, and the microcytic hypochromic trait and microcytic anemia." (PMID 37788909, 2023).
Sepsis (2 papers, 2022 to 2024). Sepsis is defined as life-threatening organ dysfunction caused by a dysregulated host response to infection. "Phospholamban (Pln), cadherin-2 (Cdh2) and Nprl3 are found to participate in the pathogenesis of sepsis and promote inflammation." (PMID 38601461, 2024). "mmu_circ_0001679 is reported to regulate the expression of Nprl3, and mmu_circ_0001212 similarly regulates Pln, Cdh2 and Nprl3 expression, which were all increased in the sepsis mice." (PMID 38601461, 2024).
sickle cell anemia (2 papers, 2015 to 2024). "Another well validated result was the association of a SNP in NPRL3 with hemolysis in sickle cell anemia." (PMID 26215470, 2015). "Perhaps by independently down-regulating expression of the HBA1/HBA2 genes, variants tagged by this NPRL3 SNP reduce hemolysis in sickle cell anemia." (PMID 26215470, 2015).
Stroke (2 papers, 2020 to 2021). Sudden impairment of blood flow to a part of the brain due to occlusion or rupture of an artery to the brain. "As a result, we found that the MPG rs2562162 (in SVD patients), MPG rs710079 (with diabetes mellitus), and NPRL3 rs2541618 (with hyperlipidemia) polymorphisms and age were associated with mortality in stroke patients." (PMID 33202874, 2020). "Interestingly, the NPRL3 rs2541618 C>T polymorphism was associated with decreased long-term survival after stroke in patients with hyperlipidemia." (PMID 33202874, 2020). "Only the C-A-C allele combination of the NPRL3 rs2541618 C>T/rs75187722 G>A/MPG rs710079 C>T polymorphisms and the T-A-C allele combination of the NPRL3 rs2541618 C>T/rs75187722 G>A/MPG rs710079 C>T polymorphisms were significantly associated with stroke prevalence after FDR analysis." (PMID 33202874, 2020). "Interestingly, NPRL3 single nucleotide polymorphism has been associated with ischemic stroke susceptibility and post-stroke mortality, which can be related with increased mTOR activity, that is known to accelerate brain recovery after stroke." (PMID 34685669, 2021). "In a further analysis, we found that some of these genotypes were associated with different stroke subtypes; specifically, SVD was associated with NPRL3 rs2541618 TT genotype, NPRL3 rs75187722 GA genotype and the dominant model, and MPG rs2562162 CT genotypes and dominant model." (PMID 33202874, 2020).
channelopathy (1 paper, 2018). Channelopathies are a group of diseases caused by the dysfunction of ion channel subunits or their interacting proteins. "Discovery of mutations in DEPDC5, NPRL2, and NPRL3 that encode for GATOR1 (negative modulator of mTORC1) have pioneered the channelopathy-independent approach in understanding the pathological process of NFLE." (PMID 30319421, 2018).
diabetes mellitus (1 paper, 2020). A metabolic disorder characterized by abnormally high blood sugar levels due to diminished production of insulin or insulin resistance/desensitization. "We found that the NPRL3 rs2541618 CT+TT genotype had synergistic effects with hypertension, diabetes mellitus, hyperlipidemia, and smoking." (PMID 33202874, 2020).
focal cortical dysplasia type II (1 paper, 2023). "For example, after a germline pathogenic truncation variant in NPRL3 was identified in a patient with focal cortical dysplasia type II (FCORD2; OMIM: #607341), a somatic missense variant in the WNT2 gene in brain-derived DNA was detected." (PMID 36672937, 2023).
gastric cancer (1 paper, 2018). A primary or metastatic malignant neoplasm involving the stomach. "To assess the involvement of TUFT1 in amino acid signaling, we utilized MKN45 human gastric cancer cells, in which the NPRL3 gene is homozygously deleted, and Kato III as control human gastric cancer cells." (PMID 29423269, 2018).
glioneuronal tumors (1 paper, 2018). "Of note, a NPRL3 variant was found in 5/8 MVNT and 90% of FCD but none of the glioneuronal tumors." (PMID 28833756, 2018).
hemoglobinopathy (1 paper, 2024). "Our case highlights that the overlap of the α-globin regulatory region MCS-R2 with the NPRL3 gene may be overlooked when performing hemoglobinopathy testing, due to the gene-centric nature of the assay." (PMID 39062615, 2024).
Intellectual disability (1 paper, 2023). "Baldassari in 201918 reported 83 patients with “language or speech delay” or “intellectual disability” out of 183 (45%), among which 75 had DEPDC5 mutations (48% of total DEPDC5 variant—155), 4 NPRL2 (40% of NPRL2 variants—10), and 4 NPRL3 (4/18, 22% of NPRL3 variants—18)." (PMID 37491868, 2023).